RNU6-27P (RNA, U6 small nuclear 27, pseudogene)
Synonyms: RNU6-27
Gene: Small nuclear RNA gene on chromosome 20 (17,187,510 to 17,187,616, forward strand). Ensembl gene ENSG00000251955.
Homologues: Orthologues: guinea pig U6 (90% identical), guinea pig U6 (84% identical). Paralogues in human: RNU6-25P (96% identical), RNU6-48P (96% identical), RNU6-1 (95% identical), RNU6-2 (95% identical), RNU6-33P (95% identical), RNU6-3P (95% identical), RNU6-4P (95% identical), RNU6-5P (95% identical), RNU6-6P (95% identical), RNU6-9 (95% identical), RNU6-12P (94% identical), RNU6-13P (94% identical), and 1286 more.